CLIC4 (CLIC family member 4)
Diseases named in the same sentence as CLIC4 in open-access papers (continued):
Sharing a sentence is not in itself a finding about the gene and the disease.
cancer (40 papers, 2012 to 2025). A tumor composed of atypical neoplastic, often pleomorphic cells that invade other tissues. "Another study showed that while CLIC4 deletion is common in tumor cells, its increased expression in the tumor stroma is associated with malignant progression in various cancers." (PMID 39595145, 2024). "In almost all cancers studied, CLIC4 is highly expressed in the cancer stroma and tightly linked to cancer progression and the formation of a myofibroblastic cancer stroma." (PMID 35727842, 2022). "Strikingly, multiple studies implicated CLIC4 in cancer progression, but the underlying molecular mechanisms remain to be elucidated." (PMID 31879279, 2020). "We found that CLIC4 expression was higher in tumor-associated fibroblasts and endothelial cells than in malignant tumor epithelial cells." (PMID 31921386, 2019). "The dependence on CLIC1/CLIC4 during MCPyV ST metastatic processes opens new insights into how viruses manipulate susceptible cells to mediate cancer progression." (PMID 29462791, 2018). "In particular, reduced CLIC4 expression and nuclear localization in cancer cells is associated with the altered redox state and CLIC4 acts as an important suppressor of squamous tumor development and progression." (PMID 24027528, 2013). "In addition, CLIC4 responds to cellular stress and contributes to both tumor suppression and cancer progression, with its expression levels associated with tumor growth and patient prognosis." (PMID 39595145, 2024). "In addition, loss of CLIC4 in tumor cells as well as gain in tumor stroma cells have been identified in multiple human cancers, which represents the malignant progression." (PMID 34440131, 2021). "CLIC4 has been implicated in angiogenesis, pulmonary arterial hypertension, epithelial differentiation, myofibroblast differentiation, response to oxidative stress, cellular adhesion and integrin trafficking, immunity, and cancer." (PMID 31921386, 2019). "However, other studies have reported that the loss of CLIC4 is a common phenotype in many human cancers and marks malignant progression; additionally, if CLIC4 was introduced into human breast cells, tumor growth is inhibited." (PMID 26816615, 2016). "The physiologic function of CLIC4 has been implicated in regulating cell cycle arrest, apoptosis, metabolic stress, cell differentiation, morphogenesis, and a novel molecular target for cancer therapy." (PMID 22761775, 2012). "Notably, many studies found an association between CLIC4 expression and cancers." (PMID 39595145, 2024). "Different mechanisms may also underlie the enhancing effects of CLIC4 on malignant tumor growth." (PMID 36230813, 2022). "The role of Chloride intracellular channel 4 (CLIC4), which plays a crucial role in cancer development and apoptosis, in FxOH-induced apoptosis was also investigated." (PMID 38609844, 2024). "Its role in angiogenesis—essential for tumor development and wound healing—highlights CLIC4’s significant impact on cancer research." (PMID 39595145, 2024). "To date, more reports and cases have uncovered the apoptosis mechanism of mammalian CLIC4 in different cancer cells." (PMID 37485065, 2023). "Among them, CLIC4 stands out since it is involved in the pathogenesis of several malignant neoplasms." (PMID 37026609, 2023). "β-integrin and CLIC4 complex are also closely related to the invasion and angiogenesis of cancer cells, and the two are likely to form a complex." (PMID 37199665, 2023). "The CIBAR1, CLIC4, OGN, and ZNF483 are protein-coding genes, but nothing is known about their association with PCa and cancer in general." (PMID 37298233, 2023). "The reduction of chloride intracellular channel 4 (CLIC4) in cancer cells is common in human tumours and signals the progression and invasion of malignant cells." (PMID 37284313, 2023). "Emerging evidence suggests that elevated CLIC4 expression is a marker for poor outcome at other cancer sites." (PMID 35727842, 2022).
cancer (continued). "CLIC4 expression was higher in cancers of younger patients relative to that of cancers from older patients." (PMID 35727842, 2022). "In human cancers, CLIC4 protein expression varies, being characteristically lost in progression of cancer cells such as those of the esophagus and colon but highly expressed in other cancer cells such as those of the ovary and pancreas." (PMID 35727842, 2022). "Generally, CLIC4 exerts detrimental effects on cancer progression, while CLIC2 shows ameliorative effects." (PMID 36230813, 2022). "The expression of CLIC4 is commonly reduced in many human cancers, including skin, breast, prostate, and lung tumors." (PMID 34440131, 2021). "We found that the expression of CLIC4 was increased in cancer tissues; however, the mRNA expression of CLIC2 and CLIC6 was lower in HCC tissues than in non-cancer tissues." (PMID 34766585, 2021). "Up-regulation of CLIC4 in tumor stroma enhances the growth of cancer xenografts and significantly involves in the process of the transforming growth factor (TGF)-β-mediated myofibroblast conversion, which is a hallmark of a nurturing tumor microenvironment." (PMID 34440131, 2021). "Considerable evidences implicate that the distribution of CLIC4 expression in many human neoplasms directly correlates with cancer pathogenesis." (PMID 34440131, 2021). "Multiple lines of evidence from previous studies in various cancer cells proposed that CLIC4 functions as a tumor suppressor." (PMID 31879279, 2020). "Specifically, an elevated expression of CLIC4, a common trait of many cancers and a marker of malignant progression, was found to be associated with the activation of the Arf6 and NF-κB signaling pathway." (PMID 33014825, 2020). "Our K-M plot analysis of human tumor mRNA data shows the CLIC4 high expression correlating with poor patient survival in all the six cancers analyzed." (PMID 32116799, 2020). "The reduction of CLIC4 in tumor cells in progressing cancers of certain organs, particularly squamous cancers, suggests a tumor suppressor role for the protein." (PMID 31921386, 2019). "Because miRNAs are heavily dysregulated in cancer and can promote tumor growth by targeting factors involved in apoptosis, one of many functions we have defined for CLIC4, we sought to identify miRNAs that can modulate CLIC4 expression." (PMID 31921386, 2019). "And the overexpression of CLIC4 in stroma increases cell migration and invasion and promotes epithelial to mesenchymal transition in multiple human cancers." (PMID 30323832, 2018). "Another study of multiple cancer types further confirmed the presence of CLIC4 in stroma surrounding the tumor nests." (PMID 30282979, 2018). "The differential transcriptional expression of CLIC4 between tumor cells and the surrounding stroma during cancer progression has been suggested to have a tumor-promoting effect." (PMID 30201851, 2018). "To evaluate the sensitivity of CLIC1 and CLIC4 staining for malignant tumor cores, we categorized the tumors based on their staining intensities and compared tumor subtypes." (PMID 30282979, 2018). "In contrast, most malignant tumors showed strong CLIC4 staining in both tumor nests and adjacent stroma." (PMID 30282979, 2018). "During cancer development, CLIC4 is downregulated in cancer cells, and it is recognized as a suppressor for tumor growth." (PMID 30201851, 2018). "CLIC4 also stained benign tumors but staining was limited to nuclei; whereas malignant tumors showed diffuse cellular staining of stromal and tumor cells." (PMID 30282979, 2018). "This is consistent with previous studies that identified the overexpression of CLIC1/CLIC4 in numerous cancer tissues including colon, prostate, pancreatic, and ovarian (26, –, 28), suggesting they directly contribute to tumor development." (PMID 29462791, 2018). "More importantly, CLIC4 gained more attention for its participation in malignant transformation, cellular stress and apoptosis of cancer cells." (PMID 26816615, 2016).
cancer (continued). "Multiple studies have investigated the expression profile and regulatory effect on the apoptosis of CLIC4 in cancer cells." (PMID 26816615, 2016). "Accumulating evidence has revealed the significant role of CLIC4 in regulating the apoptosis of different cancer cells." (PMID 26816615, 2016). "Accumulating evidence has revealed the synergistic roles played by both the mitochondria and ER in the process of CLIC4-mediated cancer cell apoptosis, findings that were consistent with ours." (PMID 26816615, 2016). "Several studies have suggested that CLIC4 regulates cancer cell apoptosis and proliferation even it displays an opposite effect in different cancer cells." (PMID 26816615, 2016). "Nonetheless, two related CLICs, CLIC1 and CLIC4, are overexpressed in cancer stem cells and envisioned as novel therapeutic targets." (PMID 26191006, 2015). "Previous studies have explored the expression and regulation of CLIC4 in cancer cells." (PMID 39595145, 2024). "In another study, CLIC1 and CLIC4 presented a high percentage of immunostaining in malignant tumors, and CLIC4 was also found in benign tumors and limited to the nucleus; it was also determined that the high expression of CLIC4 is related to a negative survival prognosis." (PMID 37375748, 2023). "The intracellular chloride channels CLIC1 and CLIC4 are promising cancer therapeutic targets because of their activities as ion channels and signal transducers in cell cycle progression and the malignant transformation of cancer cells." (PMID 37408210, 2023). "Interestingly, our research also revealed that the signal of Sig1R/β-integrin interacts with CLIC4, which have been detected in high levels in many tumors and regulates the aggressiveness of cancer cells." (PMID 37199665, 2023). "With respect to MMP14 activity, CLIC2 and CLIC4 have opposite effects, and CLIC2 may act in an inhibitory and CLIC4 in a promotive manner with respect to the metastasis and invasion of malignant tumors." (PMID 36230813, 2022). "Since host cells are the target in this study, in contrast to the usual focus on tumor-targeted therapy, a therapy developed to inhibit CLIC4 function in the host would be less likely to develop resistance as occurs in targeting heterogeneous and genomically unstable cancer cells." (PMID 35727842, 2022). "CLIC4 is a probable detrimental factor for cancer prognosis, and this may be attributable to its stimulating effect on MMP activities, opposite to CLIC2." (PMID 36230813, 2022). "Putative functions of CLIC4 that could impact its role in cancer stroma include neoangiogenesis, endothelial morphogenesis and tubulogenesis, wound healing, redox regulation, and cell adhesion." (PMID 35727842, 2022). "Therefore, it is possible that the therapeutic effect on malignant tumors will be further enhanced if not only the effect of CLIC2 is enhanced but also that of CLIC4 is inhibited at the same time." (PMID 36230813, 2022). "In addition, in many human epithelial cancers, CLIC4 expression was lost in tumor cells, whereas it was gained in tumor stroma during cancer pathogenesis." (PMID 31879279, 2020). "However, the numerous evidences for altered CLIC4 function and tumor graft studies that show a reduction in tumor formation upon altering CLIC4 expression provide enough basis to study CLIC4 as a target in cancer therapy." (PMID 32116799, 2020). "In addition, both CLIC4 and CLIC1 are overexpressed in cancer stem cells and inhibition of CLIC4 expression inhibits tumor growth." (PMID 31879279, 2020). "Thus, differential regulation of CLIC4 in cancer must be due to transcriptional/translational or post-transcriptional/translational mechanisms." (PMID 31921386, 2019). "In addition, the observation that CLIC1 overexpression can activate ERK1/2 and NF-κB p65 raises the possibility that MCPyV ST targets CLIC1/CLIC4 to regulate the mitogenic signaling pathways that contribute to cancer metastasis." (PMID 29462791, 2018).
cancer (continued). "Taken together, these results suggest that CLIC4 in cancer cells may support tumor growth and progression." (PMID 30282979, 2018). "In addition to its diverse physiological functions, the differential expression of CLIC4 between cancer cells and the surrounding stroma has been reported in various tumor types." (PMID 30201851, 2018). "Recent studies have reported that CLIC4 was a regulator for cancer cell apoptosis." (PMID 26816615, 2016). "Thus, in addition to an important function in cancer pathogenesis as a tumor suppressor, CLIC4 is emerging as a potential biomarker to monitor tumor progression and recurrence in multiple human cancers." (PMID 27289382, 2016). "CLIC4 expression reduced in tumour cells and ion channels used to inhibit cancer cell growth." (PMID 25250324, 2014). "The chloride channel (CLIC1-5) except CLIC4 became overexpressed in cancer cells." (PMID 25250324, 2014). "In the case of cancer, factors secreted by cancer cells initiate the myofibroblast transdifferentiation through a process that involves chloride intracellular channel 4 (CLIC4) upregulation as a prerequisite to the expression of the myofibroblast marker alpha smooth muscle actin (αSMA)." (PMID 22527451, 2012). "On the other hand, CLIC4 may stimulate the progression of malignant tumors." (PMID 36230813, 2022). "As PDT-mediated CLIC4 suppression is correlated to the induction of methylation in its promoter region, DNA methylation status of the promoter region might contribute to the regulation of CLIC4 expression in cancer cells." (PMID 34440131, 2021). "Interestingly, CLIC4 staining patterns varied based upon cancer stage and tumor subtype." (PMID 30282979, 2018). "Therefore, the expression profile and regulatory effect on apoptosis of CLIC4 in each specific cancer cell may be different." (PMID 26816615, 2016). "In addition, the CLIC4 gene is mapped to chromosome 1p36.11, a region that is frequently altered in cancers and thus should be considered as potential molecular target for cancer therapy." (PMID 22761775, 2012). "Chloride intracellular channel 4 (CLIC4), a member of the CLIC family, plays an important role in the development of cancer and cell apoptosis." (PMID 35736152, 2022). "Meanwhile, treatment with DNMT inhibitor, 5AZA, resulted in increased level of CLIC4 mRNA expression in CL1-0, A549 and H460 cancer cells." (PMID 34440131, 2021). "The mRNA expression level of CLIC4 in normal MRC-5 fibroblasts was significantly higher than the malignant CL1-0, A549 and H460 cancer cells, but similar to that of H1299 cancer cells." (PMID 34440131, 2021). "Yet, our study supports the emerging potential of CLIC4 and CLIC1 as a therapeutic target in cancer progression." (PMID 31879279, 2020). "The differential expression pattern of CLIC4 and CLIC1 in distinct tissues and thus in cancer types suggests a variation in their functional roles." (PMID 31879279, 2020). "All tested malignant tumors secreted CLIC1 and CLIC4 into the media and shedding was usually higher than from benign tumors." (PMID 30282979, 2018). "Across all malignant tumors, CLIC1 and CLIC4 stained 87% and 96% of the tumor cores, respectively, while CA125 stained only 75%." (PMID 30282979, 2018). "For the first time, our paper describes EIF4A1, CLIC1, PRDX6, CLIC4, ENO1, ANXA4, EMD and Ku70 in relation to EEC, although their role is well established in other cancers." (PMID 22415234, 2012). "In this context, given the functions of CLIC4 and the participation of CAF in promoting tumor growth and invasion, the present study analyzed the immunoexpression of CLIC4 and α-SMA in OSCC and OVC since these malignant neoplasms exhibit different biological behavior." (PMID 37026609, 2023).
cancer (continued). "The more notable inverse relationship between CLIC4 and miR-142-3p in stage III/IV squamous cancers suggests that miR-142-3p regulation of CLIC4 may occur predominantly in advanced cancers." (PMID 31921386, 2019). "Despite these findings, a comprehensive study of the regulatory mechanisms governing CLIC4 expression in human cancer has never been performed." (PMID 31921386, 2019). "In the case of fibroblasts, the overexpression of ClIC4 leads to the activation of the transforming growth factor-β1 (TGF-β1) and to conversion to myofibroblasts, which is a known feature of diseases characterized by the hyperproliferation of cells, including cancer." (PMID 32731552, 2020).